AXIN1 (axin 1)
Diseases named in the same sentence as AXIN1 in open-access papers (continued):
Sharing a sentence is not in itself a finding about the gene and the disease.
tumor (continued). "Our data supported that the long-term and not short-term inhibition of Notch by DAPT may enhance tumor growth and motility through up-regulation of AXIN1, CSNK2A3, and CEBPA2 genes in B-raf mutated A375 cells." (PMID 32695658, 2020). "We therefore conclude that Wnt activation in GEJ tumours is not caused by AXIN1 gene mutations." (PMID 14970870, 2004). "Recent studies reveal that overexpression of AXIN1 negatively regulates HCC cell proliferation, migration, invasion, and metastasis, significantly suppressing tumor progression." (PMID 40699663, 2025). "The direct regulatory role of AXIN1 on STING implies its potential involvement in cGAS/STING signaling, which is responsible for antiviral, anti-tumor, and inflammatory responses." (PMID 38291457, 2024). "We also detected the enrichment of proteins interacting with the ubiquitination pathway (e.g. tumour suppressors SMAD2, APC, and AXIN1)." (PMID 39660592, 2024). "By directly targeting several Wnt/β‐catenin antagonists including AXIN1, GSK3β and DKK1, miR‐31 promotes the Wnt signalling pathway and tumour development within mammary and small intestine." (PMID 38797942, 2024). "In MC38 tumor‐bearing mice, Siah1α knockdown combined with SR3029 administration synergistically inhibits CRC growth, concomitant with increased protein level of AXIN1, and downregulation of Wnt target genes." (PMID 38419282, 2024). "MiR‐31 represses tumour suppressors DACH1 and CEBPA, which otherwise direct the CD9, CD82 and AXIN1 expression." (PMID 38797942, 2024). "Similar increase was also observed in some of the key Wnt pathway genes such as CTNNB1, AXIN1 and AXIN2 suggesting a peak of immune exclusion in S2 tumours." (PMID 35301339, 2022). "In GEO cohort, AXIN1 and LEF1 were highly expressed in tumor tissues, while FZD4 and FZD2 were highly expressed in normal tissues." (PMID 36703749, 2022). "We found that AXIN1, CTNNB1 and LEF1 were highly expressed in tumor tissues and FZD4 was highly expressed in normal tissues in TCGA cohort." (PMID 36703749, 2022). "Mice in this group showed similar tumor sizes and weights, and according expression level of epithelial–mesenchymal transition molecules, including vimentin, MMP9, MMP2, AXIN-1, N-cadherin, and E-cadherin, compared to mice in the control group." (PMID 33608495, 2021). "In summary, our findings demonstrate that high LDLRAD2 expression strongly correlates tumor aggressiveness and poor prognosis, and LDLRAD2 activates Wnt/β-catenin pathway by interacting with Axin1 to EMT, invasion and metastasis of GC cells." (PMID 31649207, 2019). "Enrichment of pathways showed the interaction of these miRNAs with marked tumor suppression (PTEN, AXIN1, ATM, NLK), and important proto-oncogenes and tumor-promoting genes as MYC." (PMID 30201877, 2018). "Of the DE miRNAs, there was a marked number targeting critical tumor suppressors (PTEN, AXIN1, ATM, NLK) and critical proto-oncogenes and tumor promoting genes such as MYC." (PMID 29132323, 2017). "The homologous proteins AXIN1 and AXIN2 are components of the β-catenin destruction complex and thus, act as tumor suppressors by negatively regulating the Wnt signaling pathway." (PMID 23516639, 2013).
tumor (continued). "Given the oncogenic nature of Ephexin1 and the tumor-suppressive function of Axin1, the overexpression of Ephexin1 in CRC suggests that it could counteract the effect of Axin1, thereby promoting cancer progression." (PMID 39741188, 2025). "To explore the mechanism by which metformin induced anti-tumor immunity in H460 cells but not Axin1-/- H460 cells, we first set out to determine differences in tumor metabolism among H460, H460_met, and H460_KO_met cells." (PMID 39308524, 2024). "Our previous work demonstrated that metformin promoted the anti-tumor effect of PD-1 inhibitor in H460 cells, which have a nonsense STK11 mutation naturally, but not in Axin1-/- H460 cells." (PMID 39308524, 2024). "Furthermore, AXIN1 has been found to reduce PI3K/AKT/mTOR signaling and act as a tumor suppressor in TGCT cells." (PMID 37078359, 2023). "Hence, our study presented a tumor-promoting role of TRIM31 and a connection with Axin1 in GC, supporting a critical role of TRIM31-Axin1-β-catenin axis in GC development." (PMID 37973999, 2023). "We also found components of the β-catenin destruction complex, namely Axin1 itself and its key binding partner, the APC tumour suppressor, as well as AMER1 and β-catenin, suggesting that the entire complex is associated with Nkd1 HisC aggregates in Wnt-stimulated cells." (PMID 33025907, 2020). "The tumor suppressor APC, listed on top, interacts with AXIN1, which, in addition, interacts with other Wnt/ß-catenin signaling pathway components and is essential for degradation of ß-catenin in the Wnt/ß-catenin signaling cascade, an important signal transduction pathway in CRC." (PMID 29505855, 2018). "One tumor (patient P0027) had a complement of mutations in non-APC components (DKK1/2, CSKN1A1, and AXIN1) of the WNT pathway." (PMID 27245685, 2016). "AXIN1 protein immunohistochemistry revealed cytoplasmic expression in all tumours irrespective of the presence of AXIN1 locus LOH." (PMID 14970870, 2004). "Specifically, miR‐31 directly targets the tumour suppressors CCAAT enhancer binding protein α (CEBPA) and dachshund family transcription factor 1 (DACH1), which decreases β‐catenin protein level via increasing Wnt/β‐catenin signalling inhibitors, such as AXIN1, CD9 and CD82." (PMID 38797942, 2024). "In addition, Cluster 4 and 6 revealed no apparent driver mutation but showed aberrant expression of some tumor-related genes, such as GCM2 and AXIN1, indicating that driver gene plays an important, but not indispensable, role in the initiation of PA." (PMID 34054720, 2021). "We did not analyze the expression levels of AXIN1 in the patients' sera and tumor tissues." (PMID 31143301, 2019). "Quantitative real-time PCR experiments find that miR-31 has the most notable oncogenic targets AXIN1, which is involved in Wnt signaling pathway and forkhead family transcription factors FOXC2 and FOXP3, and this target gene and the two transcription factors are correlated with tumor stages." (PMID 29513198, 2017). "We immunostained the TMA to define each tumour as positive or negative for RUNX1 and AXIN1." (PMID 26916619, 2016).
cancer (101 papers, 2006 to 2026). A tumor composed of atypical neoplastic, often pleomorphic cells that invade other tissues. "Together, these data suggest that cancer-associated AXIN1 RGS mutations promote Wnt/β-catenin signaling by disrupting destruction complex assembly and function." (PMID 41550750, 2026). "The remaining 45 cancers carry additional truncating mutations in either AXIN1, AXIN2 or AMER1, or defective missense or truncating RNF43 mutations." (PMID 39674817, 2025). "Mutation of APC, AXIN1/2 or β-catenin itself, results in the formation of cancers with aberrantly increased β-catenin signaling, which have become largely independent of extracellular Wnt ligands." (PMID 39674817, 2025). "Of note, it has been reported that the STK11 mutation was involved in metabolic reprogramming of cancer cells, and metformin modulates metabolism predominantly through AXIN1-dependent activation of AMP-activated protein kinase (AMPK)." (PMID 39308524, 2024). "There are several genetic variants in the AXIN1 gene which their effects on cancer have been reported." (PMID 36510340, 2023). "Considering the role of AXIN1 protein in tumorigenesis, several studies evaluated the possible roles of genetic variants of the AXIN1 gene in several cancers." (PMID 36510340, 2023). "Using mutation data and focusing mainly on cancer genes, we found only one association between a subcluster of type 2, the left cluster, and mutations in Axin 1 (AXIN1)." (PMID 36321552, 2022). "Both somatic and germline mutations in the AXIN1/2 genes have been found in a subset of CRCs and in several other cancer types." (PMID 34863211, 2021). "Although aplykurodin A exhibited cytotoxic effect against HCC cells at high concentration, it is likely to be development into chemopreventive or therapeutic agent against CRT-positive cancers caused by AXIN1 mutation." (PMID 32294900, 2020). "In human cancer, AXIN1 mutations are scattered throughout the whole coding sequence of the AXIN1 gene, which results in disassembly of the β-catenin destruction complex." (PMID 32037398, 2020). "Cancer-associated APC mutations primarily comprise premature stop-codons that lead to the expression of a truncated form of the protein that lacks Axin1 interaction motifs." (PMID 25392450, 2014). "Furthermore, several cancer-associated AXIN1 missense mutations in the N-terminal RGS domain of AXIN1 were found to induce Wnt signaling and drive hyperplastic growth in Drosophila wing discs." (PMID 41550750, 2026). "AXIN1 is among the most frequently mutated genes in many types of cancer." (PMID 36361574, 2022). "Among the cancer genes, only AXIN1 is recurrently mutated in HCC according to COSMIC." (PMID 26672766, 2016). "Axin1 plays a critical role in regulating the Wnt/β-catenin signaling pathway and cancer progression, and its polymerization is indispensable for the assembly of the β-catenin destruction complex." (PMID 41461634, 2025). "In addition to the influence of genetic mutations leading to the loss of AXIN1 function, extensive research has delved into the role of epigenetic modifications, gene transcription, protein degradation, and other facets that impact AXIN1 function within the context of cancer research." (PMID 38291457, 2024). "This event activates Axin1, offering a promising strategy to combat cancers that are dependent on the WNT/β-catenin pathway." (PMID 38291457, 2024). "Targeting Axin1 deubiquitination or inducing Axin1 expression portended an anticancer strategy in some cancers." (PMID 38715121, 2024). "In cancer, proteasomal hydrolysis of Axin1 represented its weakened Wnt-regulated function and cytosolic β-catenin accumulation." (PMID 38715121, 2024). "Alterations in both Axin1 and Axin2 have been observed in various human cancers and cancer cell lines." (PMID 38534454, 2024).
cancer (continued). "The multifaceted functionalities of AXIN1 render it as a compelling candidate for targeted intervention in the realms of degenerative pathologies, systemic metabolic disorders, cancer therapeutics, and anti-aging strategies." (PMID 38291457, 2024). "These comprehensive observations underscore the intricate involvement of AXIN1 in the intricate landscape of cancer pathogenesis." (PMID 38291457, 2024). "It has been shown in previous studies that the E3 ubiquitin ligases, such as RNF146, TRIM11, TRIM32, TRIM54, TRIM65 and UBE3C promote various cancers by triggering Wnt/β-catenin signaling via degradation of Axin1." (PMID 37379772, 2023). "In the role of cancer-suppressing agents, Axin1 is a crucial component of the canonical Wnt signaling pathway, and it acts as a scaffold for β-catenin degradation." (PMID 37379772, 2023). "In the current study, we found that AXIN-1 was required for metformin to enhance T cell-mediated killing of cancer cells." (PMID 35281267, 2022). "Elucidating the downstream signaling pathways in cells with KO of AXIN1 and/or ARID1A would be necessary to define the underlying molecular mechanisms regulating their effect on cancer cell proliferation and migration." (PMID 35669430, 2022). "In control AXIN-1+/+ H460 cells, metformin together with activated T cells decreased colony formation of cancer cells." (PMID 35281267, 2022). "Another component of the destruction complex, Axin, also functions as a negative regulator of cancer growth, and two isoforms (Axin1 and Axin2) function equally in the Wnt signaling pathway." (PMID 32486158, 2020). "(d) Increased AXIN1 by Tankyrase inhibitor suppresses cell proliferation of cancer cells where Wnt/β-catenin signaling is genetically hyperactive." (PMID 32037398, 2020). "We also identified a number of ‘cancer genes'18 as significantly mutated in PDA, including BCLAF1 (5% of cases), IRF6 (4% of cases), FLG (10% of cases), AXIN1 (5% of cases), GLI3 (6% of cases) and PIK3CA (4% of cases)." (PMID 25855536, 2015). "Classically, Axin1 is viewed as a negative regulator of the Wnt/β-catenin pathway in development and cancer." (PMID 22509369, 2012). "In addition to strong signaling activity associated to β-catenin and Axin1 mutations in two well differentiated cell lines, we also observed autocrine canonical Wnt signaling in two other well differentiated cell lines, as reported for some other cancer cell lines." (PMID 19849855, 2009). "Axin-1 expression was reduced in later stages and in samples from carcinomas forming distant metastases." (PMID 16772034, 2006). "Instead, inhibition of SIAH1/2, ubiquitin ligases that regulate AXIN1 stability by associating with its more downstream GSK3 binding domain, might provide an effective strategy to stabilize AXIN1 ΔN cancer variants." (PMID 41550750, 2026). "However, in AXIN-1−/− cells, this combination had little effect in inhibiting growth of cancer cells." (PMID 35281267, 2022). "AXIN1 is an important regulator of beta-catenin, which has been found in various human cancers." (PMID 35780128, 2022). "Axin1, which functions as a concentration-limiting component of the β-catenin destruction complex, has been shown to negatively regulate the Wnt/β-catenin pathway in several cancers." (PMID 35237324, 2022). "Then we performed wound-healing and Transwell assay to ascertain whether Axin1 was involved in the anti-cancer effect of OP-B on cell migration." (PMID 34539900, 2021). "Alternations of Axin1 and Axin2 have been detected in diverse human cancers and cancer cell lines." (PMID 32486158, 2020). "In contrast, AXIN1 expression is often dysregulated in various types of cancer cells." (PMID 31569353, 2019). "In the nucleus, WTX, β-catenin, β-TrCP2, APC and AXIN1 form a new complex, and this complex could inhibit the cancer process by promoting the degradation and ubiquitination of β-catenin protein and down regulating Wnt signaling." (PMID 30939162, 2019).
cancer (continued). "Taken together, our results suggest that the transcriptional activation of AXIN1 gene by thapsigargin may provide a pharmacological basis for therapeutic intervention against Wnt-dependent cancers." (PMID 30283086, 2018). "Less frequently, loss-of-function mutation of AXIN1, AXIN2, or APC is found in 3.2%, 0.4%, and 0.2% of HCCs respectively, evidently contrasting with the situation in colorectal cancer, where up to 80% of cancers display mutated APC." (PMID 28035485, 2017). "Inhibition of TNKS1/2 by small molecule inhibitors (TNKSi) has emerged as a promising new cancer therapeutic approach as it leads to stabilization of AXIN1/2 and a concomitant reduction in β-catenin protein levels and transcriptional activity in vitro and in vivo." (PMID 27482906, 2016). "Importantly, in APC-mutant cancer cells, the distribution of Axin1 and β-catenin complexes strongly resembles that of Wnt-stimulated cells." (PMID 25392450, 2014). "We previously demonstrated that cancer-associated single amino acid substitutions within the RGS domain of AXIN1 promote unfolding and the formation of soluble nano-aggregates, leading to impaired AXIN1 polymerization, loss of APC binding, and reduced destruction complex activity." (PMID 41550750, 2026). "AXIN1's profound impact on inhibiting developmental signaling pathways and its contributions to maintaining metabolic homeostasis suggests its potential as an effective therapeutic target for conditions encompassing functional degeneration, metabolic disorders, cancer, aging, and beyond." (PMID 38291457, 2024). "In cancer, constitutive Wnt signaling can be achieved, for example, by loss‐of‐function mutations in the components of the degradation complex adenomatous polyposis coli (APC) and Axin1, which are major tumor suppressors in colorectal and hepatocellular cancer, respectively." (PMID 38135904, 2024). "Axin1 ubiquitination, degradation and subsequent liberation of β-catenin nuclear translocation are closely correlated with the activation of the expression of numerous genes that participate in most of the mechanism that leads to the development and progression of cancers." (PMID 38715121, 2024). "Stabilization of AXIN1 and AXIN2 by inhibiting their degradation through tankyrase (TNKS) allows the attenuation of Wnt signaling in cancer, attracting interest for potential targeted therapy." (PMID 39022865, 2025). "Taken together, AXIN-1 is required for metformin to stabilize STING and enhance T cell-mediated killing of cancer cells." (PMID 35281267, 2022). "The diminished expression of the tumor suppressor and Wnt signaling inhibitor Axin-1 protein in both untreated and PTX-treated PTX-res MCF-7 cells confirmed its inhibitive role on proliferation, and EMT in cancer." (PMID 33019717, 2020). "Although no published report is published on the relation between AXIN1 polymorphisms and PTC, there are several studies on the association between these variants and various cancers." (PMID 36510340, 2023). "In addition, by qPCR and RNA-seq we identified several cancer-related genes that regulated by AS of APEX1, which included AXIN1, GCNT2, SMAD3, CTBP2, PPARD, and FBXW11." (PMID 35780128, 2022). "GSK3β allows crosstalk between PI3K/AKT and Wnt pathways and antagonizes Wnt signaling by forming protein complexes with Axin1 and CK1 to polyubiquitinate β-catenin, the central component of canonical Wnt signaling, to inhibit cancer cell proliferation and invasion." (PMID 32117780, 2020).
cancer (continued). "Therefore, it seems that highly-differentiated cells have an intrinsic mechanism to target Axin1 and activate β-catenin/TCF signaling pathway, which is still maintained when the overall level of 5-HT1DR is elevated in cancer cells." (PMID 26214021, 2015). "Moreover, whereas AXIN1 is tightly controlled by tankyrase‐mediated PARsylation and ubiquitination, DCAF7 up‐regulation tracks with copy‐number gain and epigenetic/RNA‐modification changes in our pan‐cancer analysis." (PMID 41472554, 2026).